APC (APC regulator of Wnt signaling pathway)
Diseases named in the same sentence as APC in open-access papers (continued):
Sharing a sentence is not in itself a finding about the gene and the disease.
tumor (continued). "APC is a tumor-suppressor gene and an essential component of the beta-catenin complex that controls cytoplasmic beta-catenin levels." (PMID 34064046, 2021). "Furthermore, these PDZ-2 domain mutations in DLG1 seem to disable its interaction with the tumor suppressors APC and PTEN, emphasizing the importance of DLG1 functions and how alterations in its protein expression and localization might contribute to the process of oncogenesis." (PMID 34503271, 2021). "The decrease of APC level leads to the abnormal activation of Wnt signal pathway which plays an important role in the regulation of tumor immune microenvironment and regulate the infiltration and activity of various types of T cells in tumor." (PMID 33777035, 2021). "It has been reported that there were higher rates of APC hyper methylation in tumor tissues compared with normal tissues in a sample of Iranian ESCC patients." (PMID 33883026, 2021). "R-spondin receptor Lgr5, one putative mark of intestinal stem cells, is a direct target gene of the canonical Wnt signaling cascade and able to promote tumor proliferation after APC is deleted in these cells." (PMID 34381360, 2021). "APC, a tumor-suppressor gene located on chromosome 5q21-q22, is involved in CRC carcinogenesis, and Wnt/β-catenin signaling is affected by APC mutation." (PMID 33919924, 2021). "To further explore specific protein classes, we split the cohort into two groups, using supervised clustering, based on APC- and myeloid/angiogenesis-related proteins and tumor-related proteins." (PMID 34206510, 2021). "The SureSelect 92-gene custom panel detected the APC insertion in bulk tumor DNA (AF:9.8%) and also in circulating cfDNAs analyzed at two different time points (ccfDNA at diagnosis, AF: 22.6% and ccfDNA at the progression of the disease, AF:29.9%)." (PMID 34178989, 2021). "As another limitation, we did not have the necessary data to assess the association of E. coli and ETBF sero-positivity with CRC by molecular status of the tumor (e.g., MSI or APC and KRAS mutation status)." (PMID 33874856, 2021). "The oncogenic activity of RARA and tumor suppressor activity of APC observed in our study supported their roles that were reported in previous research." (PMID 35111672, 2021). "CTNNB1 mutation was both sensitive to most tumours and specific; however, a small proportion of CTNNB1 wild‐type WNT cases alternatively harbour APC mutations." (PMID 33826763, 2021). "While TNFAIP8L3 has been reported with an oncogene role, APC is a well-established tumor suppressor gene." (PMID 34540821, 2021). "We found that promoter hypermethylation at APC, TMEM101 and HCG4P3 was associated with shorter overall survival in the MCCS after adjustment for age and tumour stage." (PMID 33461604, 2021).
tumor (continued). "APC (Adenomatous Polyposis Coli Protein) is a critical tumor suppressor, initially reported as Wnt-signaling regulator." (PMID 34924953, 2021). "APC can downregulate Wnt signaling pathway by reducing the accumulation of β-catenin in the nucleus, thereby inhibit tumor growth and chemoresistance in multiple cancer types." (PMID 34852843, 2021). "We previously discovered that HBx causes resistance to bortezomib via MEK signaling and regulates the LINC01352-miR-135b-APC axis in tumor progression in HCC." (PMID 33051595, 2021). "Adenomatous polyposis coli (APC) is a tumor suppressor involved in regulation of cell growth through WNT signaling." (PMID 33883026, 2021). "APC gene is a tumor suppressor gene, coding for a protein that regulates the cytoplasm degradation of β-catenin." (PMID 34326875, 2021). "As in the metastatic setting, these data argue against employing Wnt inhibitors for APC-deficient tumours, but advocate their use for BRAF/KRAS-mutated serrated tumours that lack APC mutation (encompassing subsets of CMS1, CMS3, and CMS4 tumours)." (PMID 33673710, 2021). "The adenomatous polyposis coli (APC) gene is a key tumor suppressor gene that is involved in cell adhesion and migration, organization of the actin and microtubule networks, spindle formation and chromosome segregation." (PMID 34837901, 2021). "APC is a tumour suppressor and dictates intestinal cell differentiation fate by regulating the pyruvate metabolism process." (PMID 34059057, 2021). "The authors used a gut-specific C57BL/6J ApcMin/+/J mouse model (APC gene mutants) to evaluate parameters such as life span, tumor multiplicity, and organ index." (PMID 34950252, 2021). "Investigations have displayed that adenomatous polyposis coli protein (APC) as a tumor suppressor, casein kinase 1 (CK1), glycogen synthase kinase-3β (GSK3β), and the scaffolding protein Axin are involved in the multiprotein complex structure." (PMID 34456716, 2021). "APC plays a critical role in CRC development as a tumor suppressor gene, and its gene product inhibits Wnt/β‐catenin signaling." (PMID 34584977, 2021). "Further studies have also shown that deletion of APC in LGR5+ stem cells remaining in the crypt bottom results in tumor growth and microadenoma development in 5 weeks." (PMID 33672730, 2021). "One main tumor-suppressive function of APC is to promote intestinal differentiation through regulation of the retinoic acid (RA) biosynthesis pathway." (PMID 33987182, 2021). "These signals can help Apoptin to specifically enter tumor cells’ nuclei and interact with the APC1 subunit of APC/C, causing a C2/M cell cycle arrest and tumor cell apoptosis." (PMID 33718168, 2021). "SCNVs shared within the tumor-organoid pairs encompassed regions including BC-relevant genes, such as the tumor suppressor genes APC, PTEN, and ARID1; the oncogenes NRAS, and NOTCH1." (PMID 33371412, 2020).
tumor (continued). "APC mutation promotes CRC initiation through the activation of β-catenin and transcription-factor-4 (TCF4) complex which targets tumor progression-promoting genes, such as Myc, cyclin D1, and matrix metallopeptidase 7 (MMP7)." (PMID 33271948, 2020). "The second hit in the APC gene causes thousands of adenomatous polyps, and the accumulation of somatic mutations, including those in KRAS and BRAF, leads to tumor progression." (PMID 33060766, 2020). "With the exception of tumor 2, all tumor samples showed characteristic mutations of HNSCC including amplification of 3q26.2 (TP63, SOX2, PIK3CA), 5q14.3 (APC), 8q24.3 (PTK2), 8q22.3 (LRP12) as well as loss and/or LOH of 9p21.3 (CDKN2A)." (PMID 32426287, 2020). "Truncating mutations and subsequent loss of the APC (adenomatous polyposis coli) gene is the most common genetic event found in colon adenomas and CRC (75–90% of tumours)." (PMID 33057364, 2020). "The crosstalk between the acto–myosin network and microtubules during the mobility of astrocytes is mediated by adenomatous polyposis coli (APC), which is known to be a tumor suppressor, regulating cell differentiation." (PMID 32630739, 2020). "As a key modulator of the Wnt/β-catenin signaling pathway, APC serves as an important tumor suppressor, especially in colorectal cancer." (PMID 32327666, 2020). "Here, we demonstrate that APC affects numerous chemoresistant pathways, altering responses to different classes of chemotherapeutic agents through epithelial- and tumor microenvironment (TME)-derived mechanisms." (PMID 33105836, 2020). "The tumor suppressor genes APC and SMAD4 had an inordinately high number of frameshift or nonsense mutations." (PMID 33050525, 2020). "In the Wnt/β-catenin signaling destruction complex, the tumor suppressor APC is an essential component." (PMID 32587772, 2020). "Adenomatous polyposis coli (APC) is a tumor suppressor gene that can regulate canonical WNT signaling as a part of the multiprotein destruction complex that targets β-catenin for phosphorylation and degradation." (PMID 32328030, 2020). "Hypermethylation of adenoma polyposis coli (APC), a tumor suppressor gene, inhibits the Wnt pathway, promoting tumorigenesis and tumor progression in CRC." (PMID 32850327, 2020). "Adenomatous polyposis coli (APC), a negative regulator of the Wnt/β-catenin signaling pathway, functions as a tumor suppressor by directly interacting with β-catenin and decreasing its stability." (PMID 32456226, 2020). "The deregulation of APC/C has been reported to be connected with the genomic instability of tumor cells." (PMID 32391258, 2020). "The main mechanism by which APC exerted its tumor suppressor activity was the reduction of miR-19a, the most important member of the miR-17-92 cluster." (PMID 33276489, 2020). "The APC gene is a tumor suppressor gene, and the product of its expression is an important component of the Wnt signaling pathway, which plays a critical regulatory role in cell growth, apoptosis, and signal transmission." (PMID 32159210, 2020). "While the matched normal tissue showed both mutant and wild type alleles, the tumour tissue showed only mutant allele present and this sample was one of three to display LOH at the APC locus." (PMID 33352971, 2020). "These two observations suggest that even minor changes to APC expression have a significant impact on the tumor phenotype." (PMID 33105836, 2020).
tumor (continued). "We focused on DNA (cytosine-5)-methyltransferase 1 (DNMT1), a DNA-binding enzyme responsible for the down-regulation of many tumor suppressor genes through hypermethylation of their promoter regions and a downstream effector of APC/β-catenin/TCF4 signaling." (PMID 32225105, 2020). "In vivo fluorescence imaging of IR700 before NIR light irradiation confirmed localization of APC in tumor." (PMID 32579795, 2020). "Having established the molecular ground truth, we segregated tumour samples in the discovery cohort into LD (RSPO-fusions, RSPO-high and RNF43 mutations, n=64) and LI (APC or CTNNB1 mutations, n=347) subsets." (PMID 31563876, 2020). "In another study, Almeida and colleagues showed that APC/C-induced degradation of 6-phosphofructokinase significantly suppressed glycolysis, and thus proliferation, in tumor cells." (PMID 32051488, 2020). "Of these, the most frequently mutated genes were CREBBP and CASC5 in all three tumor types, HNF1A and APC in both PDACs and PNETs, while two, four, and eight genes were mutated only in PDACs, PNETS, and INETs, respectively." (PMID 32586046, 2020). "It is confirmed that APC acts as an antagonist of the Wnt signaling pathway in several cancer types, and the low expression of APC promotes tumor progression." (PMID 33363011, 2020). "In a murine model of CRC (APC +/−), the introduction of F. nucleatum increased tumor multiplicity and the selective recruitment of myeloid cells infiltrating tumors, thereby promoting tumor progression." (PMID 33272322, 2020). "Although the tumor suppressive effect of APC has been established in a wide range of tumors, the function of APC2 has only been recognized in a limited number of tumors." (PMID 32951505, 2020). "Tumor cells, as a special type of APC, often process self‐antigen peptides through the proteasome and endoplasmic reticulum system." (PMID 32476259, 2020). "Hypermethylation of APC is observed in PCa tumours and a number of studies have demonstrated its prognostic potential." (PMID 33076494, 2020). "Both APC and BRAF mutations are tumor-initiating events and give rise to different precursor lesions." (PMID 32384699, 2020). "As we had anticipated, in all of the tumor tissues, APC was altered, consistent with this being one of the first acquired mutations in CRC." (PMID 32825052, 2020). "In the absence of Wnts, β-catenin is degraded via a destruction complex consisting of tumor suppressors such as adenomatous polyposis coli (APC), Axin, glycogen synthase kinase-3β (GSK3β), and casein kinase 1 (CK1)." (PMID 33126517, 2020). "She did not carry any germline cancer-associated variants and tumor targeted gene sequencing showed somatic mutations in APC, KRAS, and FBXW7 in the primary tumor sample." (PMID 30850667, 2019). "The concordance for APC methylation in plasma DNA vs. HCC tumor tissue was almost 82%, with sensitivity and specificity of 78% and 90%." (PMID 31673629, 2019). "APC is a tumor suppressor gene and has many functions that affect the progression of cancer cells, such as proliferation, migration, cytoskeletal maintenance, and chromosome instability." (PMID 31336886, 2019).
tumor (continued). "Together, our results indicated that in APC-mutated CRC tumors, WDR76 plays a role as a tumor suppressor by repressing RAS protein abundance and thus reducing the activation of the Wnt/β-catenin pathway." (PMID 31362761, 2019). "It influences the expression of specific genes such as GSK-3β and APC (up-regulation) and β-catenin (down-regulation) which promote the apoptosis of tumor cells." (PMID 31905725, 2019). "To do this, we administered MSC2504877 (30 mg/kg) to mice bearing APC mutant COLO320DM tumour cell xenografts and recovered tumours for analysis 2–18 hours later." (PMID 30655555, 2019). "The transition from a normal to hyperplastic epithelium is frequently linked to the inactivation of the adenomatous polyposis coli (APC) tumor suppressor." (PMID 31289620, 2019). "DKK2 blockade introduced by anti-DKK2 antibody suppressed tumor growth and enhanced the effects of cytotoxic immune cells in APC mutant NSCLC, in consistent with the previous study in colorectal cancer." (PMID 31372243, 2019). "The mutations identified in APC, GNAS, and BRAF were found in serous (1/64, 1.6%), endometrioid (1/5, 20.0%), and mucinous (1/1, 100.0%) tumor samples, respectively." (PMID 31197119, 2019). "TASIN-1′s administration into xenograft and mouse models has shown its effectiveness in tumor suppression and its specificity in killing cells with truncated APC’s while sparing normal cells in vivo." (PMID 31382613, 2019). "Deletion of N-WASP in the intestinal epithelium promotes tumor frequency in small intestine in the APC+/− model, although tumor sizes strongly decreased." (PMID 31608298, 2019). "A genetic mutation was identified in two samples: an APC gene mutation and an STK11 mutation, the location of which corresponded to the tumour sample mutations seen in these patients." (PMID 30774772, 2019). "The results for top-ranked regulators indicated that different E2F family members exhibited significantly reduced transcriptional activities upon oxamate treatment whereas tumor suppressive regulators, including APC complex and RB, showed enhanced activities." (PMID 30813560, 2019). "In the first instance, we assessed the cell inhibitory properties of MSC2504877 in an isogenic pair of APC wild type (APCWT) and APC defective (APC−/−) cells lines derived from the MCF10A non-tumour epithelial cell line." (PMID 30655555, 2019). "We found, both in cases and controls, that neither the age at prostate biopsy nor the time interval between two negative biopsies were associated with methylation of GSTP1, APC, C1orf114, GABRE, PITX2, or LINE-1 in non-tumor prostate tissue." (PMID 31666119, 2019). "Concurrently, Wnt/β-catenin perturbation is regarded a major initiating event in development of CRN as its tumor-suppressor gene adenomatous polyposis coli (APC) is inactivated in about 80% of sporadic colorectal cancers, CRC." (PMID 31253108, 2019). "As for MAPK signalling in RAS-mutant tumours, a modulation of β-catenin and the Wnt signalling pathway has been described in APC-mutant CRC." (PMID 31758153, 2019). "Along these lines, we chose to study yet an additional tumor suppressor pathway, APC and its β-catenin pathway, important culprits in the development of colorectal tumors." (PMID 31024258, 2019). "APC is a well-known tumor suppressor that is frequently inactivated due to hypermethylation of its promoter region." (PMID 31631067, 2019).